FOXE1 (forkhead box E1)
Description:
Transcription factor that binds consensus sites on a variety of gene promoters and activate their transcription. Involved in proper palate formation, most probably through the expression of MSX1 and TGFB3 genes which are direct targets of this transcription factor. Also implicated in thyroid gland morphogenesis. May indirectly play a role in cell growth and migration through the regulation of WNT5A expression.
Synonyms: HFKL5; TTF-2; FKHL15; FOXE2; TITF2; TTF2; HFKH4; BAMLAZ; NMTC4
Tractability: No criterion of Open Targets' tractability assessment is met for any kind of drug.
Gene: Protein-coding gene on chromosome 9 (97,853,226 to 97,856,717, forward strand). Ensembl gene ENSG00000178919.
Subcellular location: Nucleus
Gene Ontology:
Molecular function: DNA-binding transcription factor activity; DNA-binding transcription factor activity, RNA polymerase II-specific; protein binding; sequence-specific DNA binding; sequence-specific double-stranded DNA binding; RNA polymerase II cis-regulatory region sequence-specific DNA binding; DNA binding
Biological process: chordate pharynx development; hard palate development; positive regulation of DNA-templated transcription; regulation of transcription by RNA polymerase II; soft palate development; thymus development; thyroid gland development; anatomical structure morphogenesis; cell differentiation; cell migration; embryonic organ morphogenesis; hair follicle morphogenesis; thyroid hormone generation; animal organ development; cellular response to insulin stimulus; cranial skeletal system development; negative regulation of DNA-templated transcription; regulation of DNA-templated transcription; roof of mouth development; system development
Cellular component: nucleus; chromatin
Genetic constraint (gnomAD): Loss-of-function variants: 4 observed, 2.77 expected, observed/expected ratio (o/e) 1.45, 90% interval 0.63 to 1.93. That is too few expected variants to judge how well the gene tolerates losing a copy. Missense variants: 574 observed, 455.28 expected, observed/expected ratio (o/e) 1.26, 90% interval 1.18 to 1.35. Synonymous variants: 277 observed, 211.53 expected, observed/expected ratio (o/e) 1.31, 90% interval 1.19 to 1.45.
Gene-disease validity (ClinGen):
ClinGen rates the evidence that FOXE1 causes each of these diseases.
Bamforth-Lazarus syndrome (autosomal recessive): Definitive. Bamforth-Lazarus syndrome is a very rare syndrome of congenital hypothyroidism characterized by thyroid dysgenesis (in most cases athyreosis), cleft palate and spiky hair, with or without choanal atresia, and bifid epiglottis.
Homologues: Orthologues: chimpanzee FOXE1 (99% identical), macaque FOXE1 (97% identical), pig FOXE1 (92% identical), dog FOXE1 (90% identical), mouse Foxe1 (89% identical), rat Foxe1 (88% identical), tropical clawed frog foxe3 (40% identical), zebrafish foxe3 (39% identical). Paralogues in human: FOXE3 (40% identical), FOXC2 (32% identical), FOXC1 (30% identical), FOXA2 (27% identical), FOXD1 (27% identical), FOXD3 (26% identical), FOXL1 (26% identical), FOXB1 (26% identical), FOXD4 (26% identical), FOXD4L1 (25% identical), FOXD4L3 (25% identical), FOXD4L5 (25% identical), and 29 more.
Diseases named in the same sentence as FOXE1 in open-access papers:
FOXE1 is named in the same sentence as 87 diseases in open-access papers, as found by Europe PMC text mining. Sharing a sentence is not in itself a finding about the gene and the disease. The quoted sentences say what the papers report.
thyroid cancer (51 papers, 2009 to 2025). "Germline variants in the FOXE1 transcription factor have been associated with thyroid ectopy, cleft palate (CP) and thyroid cancer (TC)." (PMID 38396644, 2024). "FOXE1 has been widely studied as a thyroid-specific transcription factor in thyroid cancer, and its polymorphisms (rs965513 and rs1867277) are thought to increase susceptibility to thyroid cancer." (PMID 38734646, 2024). "Overall, the results of this study reinforce the role of FOXE1 variants in cases of thyroid ectopy, cleft palate and thyroid cancer." (PMID 38396644, 2024). "MYH9 binds to lncRNA gene PTCSC2 (Papillary Thyroid Carcinoma Susceptibility Candidate 2) and regulates FOXE1 (Forkhead box protein E1) in the 9q22 thyroid cancer risk locus." (PMID 37175943, 2023). "The same group identified a rare FOXE1 variant (p.A248G) which co-segregated with thyroid cancer in one family and was also present in a case of sporadic NMTC." (PMID 35255942, 2022). "The authors also observed an association between FOXE1 polyalanine tract expansions and familial thyroid cancer risk (OR = 2.56)." (PMID 35255942, 2022). "In a genome-wide association study in a population of 192 and 37,196 thyroid cancer cases and controls, seven of the nine strongest association signals were in a similar linkage disequilibrium region as the FOXE1 gene." (PMID 35255942, 2022). "The transcription factor FOXE1, essential for thyroid organogenesis and function, has been identified as susceptibility gene for differentiated thyroid cancer." (PMID 34299284, 2021). "This study investigates the impact of a SNP, rs965513 at the FOXE1 locus, on predisposition to differentiated thyroid cancer in a Western European patient population." (PMID 37435181, 2021). "Mutations in FOXE1 are associated with thyroid phenotypes including congenital hypothyroidism, thyroid dysgenesis and thyroid cancer." (PMID 37435181, 2021). "The BRAFV600E-dependent mouse model of thyroid cancer with a single functional FOXE1 allele (FOXE1+/-) was then used to test if the identified genes were under FOXE1 control, also in vivo." (PMID 34299284, 2021). "Forkhead box E1 (FOXE1) is a lineage-restricted transcription factor involved in thyroid cancer susceptibility." (PMID 34299284, 2021). "More recently, genome-wide association studies have highlighted a novel role of FOXE1 as a susceptibility gene for thyroid cancer by identifying several non-coding SNPs linked to increased risk of developing PTC." (PMID 33375029, 2020). "Here, we investigate if FOXE1 gene dosage is able to influence the outcome of experimental thyroid carcinoma in vivo by using a BRAF oncogene-induced thyroid cancer model with heterozygous Foxe1 knockout allele." (PMID 33375029, 2020). "Recently, FOXE1, a transcription factor expressed in the thyroid since early developmental stages and throughout adult life, has been associated with thyroid cancer susceptibility." (PMID 33375029, 2020). "In PTC, MYH9 binds the lncRNA gene, PTCSC2, to modulate FOXE1 in the 9q22 thyroid cancer risk locus." (PMID 32982961, 2020). "Despite these evidences, the demonstration of a cause-effect relationship between FOXE1 expression levels and thyroid cancer phenotype in vivo is still missing." (PMID 33375029, 2020). "Mice heterozygous for FOXE1 null allele (FOXE1+/−) were crossed with a BRAFV600E-inducible cancer model to develop thyroid cancer in either a FOXE1+/+ or FOXE1+/− genetic background." (PMID 33375029, 2020). "Recently, FOXE1 expression levels have been positively associated with thyroid cancer differentiation degree, however the same study shows that silencing of FOXE1 in vitro decreases migratory and the invasive ability of thyroid cells." (PMID 33375029, 2020). "It is important to conduct a meta-analysis to assess the association between FOXE1 including rs965513, rs944289 and rs1867277 and differentiated thyroid cancer." (PMID 29788924, 2018).
thyroid cancer (continued). "The common genetic variation of FOXE1 has been identified as a new research hotspot in the susceptibility of differentiated thyroid cancer." (PMID 29788924, 2018). "On this regard, it has been reported that the rs1867277A allele recruits the USF1/USF2 transcription factors and has been shown to be involved in an allele-specific transcriptional regulation of FOXE1 in thyroid cancer." (PMID 28928994, 2017). "The rs965513 polymorphism located near FOXE1 was first identified as significantly associated with thyroid cancer by Gudmundsson J in 2009." (PMID 27191655, 2016). "Co-regulation of TERT suggests a mechanism by which allelic variants in/near FOXE1 are associated with thyroid cancer risk." (PMID 27852061, 2016). "The region overlapped with the promoter region of FOXE1, and the variability of genotypes was associated with differential activity levels of an enhancer, further leading to variations in FOXE1 expression that resulted in altered risk of thyroid cancer." (PMID 27191655, 2016). "Although FOXE1 was initially recognized for its role in thyroid organogenesis, more recently a strong association has been identified between the FOXE1 locus and thyroid cancer." (PMID 27852061, 2016). "We therefore performed a meta-analysis of the published studies to clarify this inconsistency and to establish a comprehensive picture of the relationship between common variants on chromosome FOXE1 and thyroid cancer." (PMID 24489898, 2014). "It has been suggested to tag a functional variation near the FOXE1 gene which contributes to an increased risk of developing thyroid cancer." (PMID 24489898, 2014). "Over the past few years, these polymorphisms (rs965513, rs1867277, and rs71369530) in the FOXE1 region and thyroid cancer risk have been independently replicated by subsequent studies." (PMID 24489898, 2014). "Recently, genome-wide association studies have identified FOXE1 as a thyroid cancer (TC) susceptibility gene in populations of European descent." (PMID 24489898, 2014). "Common genetic variant (rs965513) of FOXE1 at chromosome 9q22, has been identified as a new hotspot for thyroid cancer susceptibility by a recent GWA study." (PMID 24489898, 2014). "This approach constitutes a successful approximation to define thyroid cancer risk genes related to individual susceptibility, and identifies FOXE1 as a key factor for its development." (PMID 19730683, 2009). "Another study revealed that the TFs ELK1 and Forkhead box protein E1 (FOXE1) interact, and this interaction may be associated with thyroid cancer risk." (PMID 40862737, 2025). "Moreover, FOXE1’s expression levels have been positively associated with the degree of thyroid cancer differentiation, as less differentiated tumours such as anaplastic thyroid cancers present low or null FOXE1 expression." (PMID 38396644, 2024). "In addition, multiple studies have also suggested that rare variants and SNPs in the FOXE1 gene locus are strongly associated with thyroid cancer (both familial and sporadic) and cleft palate." (PMID 38396644, 2024). "Loss- and gain-of-function studies of FOXE1 in thyroid cancer cells show that FOXE1 may be an EMT modulator (Morillo-Bernal, Fernandez, and Santisteban 2020)." (PMID 36994096, 2023). "Additionally, the rs965513polymorphism of FOXE1 has been associated with sporadic andfamilial cases of thyroid cancer." (PMID 34617949, 2021). "Recently, we demonstrated that FOXE1 dosage alteration affects thyroid cancer histology, proliferation and differentiation in vivo, thus showing for the first time a cause–effect relationship between FOXE1 and thyroid cancer phenotype." (PMID 34299284, 2021). "Finally, we confirmed that the most frequent FOXE1 poly-A variant in our panel of thyroid cancer cells is FOXE114Ala followed by FOXE116Ala." (PMID 31846430, 2020).
thyroid cancer (continued). "Given that FOXE1 has been described as a susceptibility gene in thyroid cancer, we first compared its level of expression in a panel of human thyroid cancer cell lines with its expression in the normal (immortalized) thyroid follicular cell line NThy-ori-3-1 (NThyOri)." (PMID 31846430, 2020). "Interestingly, a strong association has been recently described between FOXE1 expression and susceptibility to thyroid cancer, but little is known about the mechanisms underlying FOXE1-induced thyroid tumorigenesis." (PMID 31846430, 2020). "Although MYH9 binds to lncRNA gene PTCSC2 and regulates FOXE1 in the 9q22 thyroid cancer risk locus, mechanistically, the detailed role of MYH9 in PTC is still unknown." (PMID 32982961, 2020). "Besides the morphological differences, we highlighted that reduced FOXE1 function induces a more pronounced loss of follicular cell differentiation, a feature commonly associated with more aggressive thyroid cancers." (PMID 33375029, 2020). "Single nucleotide polymorphisms (SNPs) in FOXE1 and its promoter regions have been associated with various etiologies related to the thyroid, including orofacial clefting, specially cleft palate (CP) and CL, hypothyroidism (HT), and thyroid cancer." (PMID 28928994, 2017). "However, the effect of FOXE1 variants on thyroid cancer risk seemed to be less significant than that of NRG1 in this Asian population." (PMID 28703219, 2017). "Among the identified SNPs, the rs965513 polymorphism, which is the most robust among the previously identified locus (FOXE1, 9q22.33), was associated with a significantly increased risk of thyroid cancer with an odds ratio (OR) of 1.80 in Caucasians in a meta-analysis." (PMID 28703219, 2017). "Finally, with respect to the association between variants in/near FOXE1 and mechanisms of thyroid cancer risk, our data provides a new mechanism by which FOXE1 can affect cancer development via TERT upregulation." (PMID 27852061, 2016). "Little is known about the role of FOXE1 in the adult thyroid gland, or about those mechanism(s) by which variants in or near FOXE1 (all of which are in tight linkage disequilibrium) are associated with thyroid cancer risk." (PMID 27852061, 2016). "However, as of yet, no mechanistic data exists to explain the association between FOXE1 and thyroid cancer risk." (PMID 27852061, 2016). "In addition to the rs965513 polymorphism, two other variants of FOXE1, rs1867277 and rs71369530, are also significantly associated with thyroid cancer." (PMID 27191655, 2016). "We hypothesized that identifying FOXE1 transcriptional partners would shed light on the mechanism of its association with thyroid cancer." (PMID 27852061, 2016). "Mutations in FOXE1 have been implicated in hypothyroidism and thyroid cancer." (PMID 25436638, 2014). "In addition to hypothyroidism, FOXE1 has previously been associated with thyroid cancer and TSH levels." (PMID 22493691, 2012). "Thus, FOXE1 expression seemed to be downregulated both at the RNA and protein levels in tumours, independently of the presence of variants in the gene promoter, which parallels the progressive dedifferentiation in thyroid cancer development." (PMID 38396644, 2024). "Recently, a case-control study conducted in Iran on 81 patients with thyroid cancer and 165 controls found that FOXE1 polymorphism (rs1867277) could be used as a biomarker for thyroid cancer diagnosis, being found in 32.1% (homozygous GG) and 18.5% (homozygous AA) of thyroid cancer patients." (PMID 37189693, 2023). "This is the first time, to the best of our knowledge, that FOXE1 has been connected to the expression of immune-related genes, thus paving the way to novel perspectives to understand the contribution of such a transcription factor to thyroid cancer susceptibility." (PMID 34299284, 2021).
thyroid cancer (continued). "Furthermore, the polymorphism in the length of the poly-A tract of FOXE1 (rs71369530), which has been associated with thyroid cancer, has been demonstrated to be in tight linkage disequilibrium with rs1867277, in addition to being associated (FOXE116Ala) with PTC." (PMID 31846430, 2020). "Interestingly, most of the identified SNPs fall into putative regulatory regions of the FOXE1 locus, suggesting that different susceptibilities to thyroid cancer could be determined by variable expression level of FOXE1." (PMID 33375029, 2020). "This concept that impaired FOXE1 function drives thyroid oncogenesis is also supported by recent description of a germline missense FOXE1 mutation in one family with non-medullary thyroid cancer, and also by finding somatic FOXE1 missense mutations in sporadic thyroid cancer." (PMID 27852061, 2016). "This hypothesis is supported by the reported loss of USF activity in breast cancer cells, and impairment of the recruitment of USF factors to specific E-box elements due to SNPs, as observed in the variant rs1867277 FOXE1 gene, conferring thyroid cancer susceptibility." (PMID 22291606, 2012). "Recent studies have found that FOXE1 is closely related to the occurrence and development of many human tumors, including thyroid cancer, pancreatic cancer, skin cancer, and breast cancer." (PMID 38734646, 2024). "FOXE1 mRNA expression was assessed in the tumours and matched adjacent normal tissue from the F1 and F2 probands and three unrelated thyroid cancer cases from our cohort." (PMID 38396644, 2024). "Recently, several polymorphisms in regulatory and/or coding regions of the transcription factor FOXE1 have been associated with increased susceptibility to PTC and aggressive forms of thyroid cancer." (PMID 34299284, 2021). "To further investigate the phenotypic effects of FOXE1 level variation on thyroid cancer, here we combined two complementary approaches: gain-of-function in vitro and loss-of-function in vivo." (PMID 34299284, 2021). "We then asked if FOXE1 was able to regulate macrophage infiltration in thyroid cancers in vivo by using a mouse model of cancer, either wild type or with only one functional FOXE1 allele." (PMID 34299284, 2021). "IHC for α-SMA reveals that reducing FOXE1 levels in BRAFV600E-induced thyroid cancer decreases the CAFs stromal expansion observed in FOXE1 wild type background." (PMID 34299284, 2021). "Despite the identification of numerous FOXE1 variants associated with PTC risk, it is poorly understood how they modulate thyroid cancer susceptibility at the molecular level." (PMID 34299284, 2021). "We have recently shown that genetic reduction of FOXE1 dosage modifies multiple thyroid cancer phenotypes." (PMID 34299284, 2021). "In vitro studies in thyroid cancer cell lines revealed that FOXE1 modulates cell migration, suggesting a role in epithelial-to-mesenchymal transition." (PMID 33903625, 2021). "We then checked if FOXE1 was also involved in a similar phenotype in vivo in a thyroid cancer model with heterozygous FOXE1 knockout." (PMID 34299284, 2021). "In conclusion, this study highlights a novel function of FOXE1 in modulating TAMs infiltration and stromal organisation in differentiated thyroid cancer." (PMID 34299284, 2021). "To answer this question, we used a FOXE1+/+ and FOXE1+/- BRAFV600E-dependent thyroid cancer mouse model (BRAF) to induce thyroid cancer in the presence of reduced FOXE1 expression." (PMID 34299284, 2021). "In conclusion, we have identified ZEB1 as a bona fide target of FOXE1 in thyroid cancer cells, which provides new insights into the role of FOXE1 in regulating EMT in thyroid cancer." (PMID 31846430, 2020).